TIGIT (T cell immunoreceptor with Ig and ITIM domains)
Diseases named in the same sentence as TIGIT in open-access papers (continued):
Sharing a sentence is not in itself a finding about the gene and the disease.
infection (continued). "The relative expression level of TIGIT downregulated in the PBMCs and spleens of infected mice on the first day after infection, while the expression of costimulatory receptor CD226 in the spleen of infected mice increased significantly." (PMID 33629951, 2021). "After high-dose Ad-HBV-Luc infection, we also detected HBV-specific CD8 T cells with elevated levels of PD1, TIGIT and TOX, markers associated with T cell dysfunction." (PMID 34835079, 2021). "CD4 T-cell counts correlated inversely with the amounts of proliferated TIGIT+NK (r = −0.63, P = 0.007) and TIGIT−NK cells (r = −0.68, P = 0.003) only in the first month of infection." (PMID 33717085, 2021). "Compared with the Nc (normal control) group, TIGIT expression on splenic CD4+ T cells of mice was significantly upregulated from the 1st week after PRU cyst infection to the 12th week after infection (p < 0.01)." (PMID 34421855, 2021). "Strikingly, the frequency of CD69 expression on TIGIT+NK cells at different stages of infection was significantly higher than the TIGIT−NK counterparts (all P < 0.0001) and both subsets were higher than their respective HIV-1-negative donors." (PMID 33717085, 2021). "At the same time, compared with the control group, CD226 expression on splenic T cells was significantly downregulated only in the 1st week after infection, which was negatively correlated with the expression of TIGIT." (PMID 34421855, 2021). "Our study showed that engagement of the TIGIT pathway limited infection-induced liver and lung damage in an IL-10-dependent manner, thus revealing a critical mechanistic aspect of TIGIT biology." (PMID 32152316, 2020). "T cells are known to upregulate the express of checkpoint molecules including PD-1, TIM-3, and TIGIT in response to variable cases, such as inflammation and infection, to maintain immune homeostasis." (PMID 31007604, 2019). "Strikingly, elevation of TIGIT expression levels was detected in longitudinal samples from HIV infected subjects treated from early infection." (PMID 28084312, 2017). "We found that diminished TIGIT expression in CD8+ T cells of ECs was predominantly localized to activated CD8+ T cells during the acute to chronic infection phase (49, 84, and 133 days post-infection), whereas in resting CD8+ T cells, this reduction was only evident at 133 days post-infection." (PMID 40637373, 2025). "Additionally, we observed clonal expansion of Areg-expressing TIGIT+ Treg cells during infection, emphasizing the antigen-driven expansion of this tissue repair Treg cell subset." (PMID 41094201, 2025). "Thus, in Treg cells, TIGIT directly induces Areg in a cell-intrinsic manner following infection, and TIGIT expression on Treg cells is essential for TIGIT-mediated protection from pathology following infection." (PMID 41094201, 2025). "Notably, ECs exhibited significantly lower BTLA expression in activated CD4+ T cells (49 and 133 days post-infection) and TIGIT expression in activated CD8+ T cells (49, 84, and 133 days post-infection)." (PMID 40637373, 2025). "Engagement of alloantigens with CD4 T cell TCR from the transplanted allograft or autoantigens uncovered by ischemia reperfusion injury after transplantation is a possible mechanism through which TIGIT becomes upregulated prior to exposure to infection-related antigens." (PMID 40475763, 2025). "Indeed, frequencies of Areg+ cells were highest among TIGIT+ Treg cells compared to their TIGIT− counterparts, and the infection-induced increase in Areg was restricted to this population." (PMID 41094201, 2025). "There was a significantly reduced percentage of CD4+ T cells-expressing TIGIT following infection." (PMID 39109867, 2024). "Importantly, TIGIT-KO had a better survival rate compared to the WT mice, and all TIGIT-KO mice survived the infection." (PMID 39109867, 2024).
infection (continued). "Conversely, the percentage of TIGIT expression in CD4+ cells in the liver of WT mice was decreased for an unknown reason following infection with C. albicans, though it either increased or remained unchanged in NK and CD8+ cells, respectively." (PMID 39109867, 2024). "Overexpression of TIGIT by lentivector infection could hinder the function of CD4+ T cells, such as diminished IFN-γ and IL-17 production, and increased IL-10 expression." (PMID 35720417, 2022). "We next wanted to test whether C. albicans recognition by TIGIT is a functional immune-evasion mechanism in vivo, or whether it is a host-beneficial mechanism that can protect it from infection related immunopathology." (PMID 35513379, 2022). "Moreover, expression of TIGIT on NKG2A−NKG2C+NK cells was greater than that on NKG2A+NKG2C−NK cells in both HIV-1-infected individuals at different stages of infection as well as in healthy donors (all P < 0.05)." (PMID 33717085, 2021). "During the infection process, TIGIT expression in T cell subsets within PBMCs and spleens from the infection group decreased on the third day post infection; this trend was more obvious in CD4+ T cells, but it only lasted until the fifth day after infection in CD4+T cells within PBMCs." (PMID 33629951, 2021). "TIGIT expression on NK cells did not frequently increase in the early phase of infection, though the frequency of TIGIT-expressing NK cells was positively associated with HIV-1 viral load." (PMID 33717085, 2021). "This study found that, different from our previous studies on acute T. gondii infection, T. gondii could be detected in the spleen from 1 to 3 weeks post infection, and TIGIT expression on T cells was significantly upregulated." (PMID 34421855, 2021). "Infection with Plasmodium yoelii could induce high expression of TIGIT on splenic CD4+T cells in infected mice." (PMID 33629951, 2021). "TIGIT expression on splenic CD8+ T cells returned to the normal level, but the expression of TIGIT in spleen increased again 9 weeks after infection, which may be related to the partial activation of T. gondii in mice." (PMID 34421855, 2021). "Compared with those in the control group, TIGIT mRNA expression in spleen was prominently upregulated at the 1st and 12th week post infection (p < 0.01), and the mRNA level of TIGIT was prominently downregulated at the 3rd and 9th week post infection (p < 0.01)." (PMID 34421855, 2021). "We found that TIGIT expression on splenic T cells increased significantly post infection." (PMID 34421855, 2021). "Interestingly, CD38/HLA-DR coexpression on TIGIT+NK cell population was higher than the TIGIT−NK cell population in HIV-1-infected individuals who were at different phases of infection and in HIV-1-negative donors (all P < 0.05)." (PMID 33717085, 2021). "Also, the higher the levels of HIV-1 viral load, the more CD69-expressing TIGIT+NK cells and TIGIT−NK cells were detected at the acute stage of infection (TIGIT+NK: r = 0.33, P = 0.052; TIGIT−NK: r = −0.53, P = 0.001)." (PMID 33717085, 2021). "Indeed, antigen-specific T cells expressed high levels of TIGIT during the chronic phase of the infection starting from day 20 p.i., suggesting that like PD-127,28, TIGIT expression is maintained in response to continuous TCR stimulation." (PMID 32152316, 2020). "De novo infection also induced expression of TIGIT on infected cells." (PMID 26735971, 2016). "Similarly, at the protein level, Areg induction was severely impaired in both the spleen and lung of Tigit-KO mice after both LCMV and influenza infection, but not in steady-state Treg cells, demonstrating a functional link between TIGIT and Areg following infection." (PMID 41094201, 2025). "Furthermore, TIGIT blockade or deletion severely impaired Areg expression and reduced the entire transcriptional repair signature in T cells, highlighting the importance of TIGIT in tissue repair following infection." (PMID 41094201, 2025).
infection (continued). "Therefore, it is likely that the activated TIGIT+Helios+ T cells we identified may have an immunosuppressive function during infection." (PMID 35651622, 2022). "Similarly, P14 T cells expressed more TOX in MOG-GP than WT mice at 21 days after i.c. infection which was associated with an elevated expression of PD-1, TIGIT, LAG-3 but not TIM-3." (PMID 33579927, 2021). "In addition to elevated levels of CD44, Tregs in IFNARflf/fl x Foxp3YFP-Cre mice also expressed higher percentages of other activation markers, including Ki-67+, ICOS+ and TIGIT+, consistent with an activated phenotype and greater degree of proliferation at day 5 post Armstrong infection." (PMID 29672594, 2018). "In addition to TIGIT, a number of other inhibitory receptors linked to immune dysfunction, such as PD-1, CD160 and 2B46, 7, 9, 10, 12, 13, are expressed on HIV-specific CD8+ T cells during the course of infection." (PMID 28084312, 2017). "We further uncover a signaling axis in which the engagement of TIGIT and TCR induces the transcription factor Blimp-1, which then directly drives Areg transcription to facilitate tissue repair following infection." (PMID 41094201, 2025). "In both the Em1m and Em3m groups, infection markedly increased IL-22 expression and concurrently up-regulated the immune checkpoint molecules CD155 and its receptor TIGIT, thereby establishing an immune-tolerant microenvironment." (PMID 41562076, 2025). "However, the mechanism of immune cell failure caused by pathogen infection, as well as whether this process is related to TIGIT, has not been well studied until now." (PMID 33629951, 2021). "In contrast, Ad-HBV-Luc infection with 107 pfu/mouse resulted in initial upregulation of PD1 and TIGIT on HBV-specific CD8 T cells followed by decreased expression at day 30 when the infection was cleared." (PMID 34835079, 2021). "On the 3rd and 7th days post infection, the TCM subset of T. gondii-specific TIGIT+CD4+ T cells in the spleen was activated and transformed into TEM cells." (PMID 33629951, 2021). "Further, at different stages of infection, CD96−CD226+ cells diminished among total NK cells, TIGIT+NK and TIGIT−NK cells, while CD96+CD226− cells expanded." (PMID 33717085, 2021). "In this study, T. gondii-specific TIGIT+ TEM cells in the spleen increased on the 3rd and 7th days post infection, indicating that TCM cells were triggered to differentiate into TEM cells due to the increase in parasite load and antigen stimulation." (PMID 33629951, 2021). "During the chronic phase of the infection (day 30 p.i.), CD8+ T cells from anti-TIGIT-treated mice displayed markedly lower PD-1 and Tim-3 expression levels than controls." (PMID 32152316, 2020). "We found that TIGIT is indeed highly expressed during the course of chronic LCMV clone 13 infection on both CD4+ and CD8+ T cells as well as on Tregs, the latter displaying the highest expression of TIGIT throughout the course of infection." (PMID 32152316, 2020). "We calculated the contribution of cells expressing PD-1, TIGIT or LAG-3 to the total reservoir by taking into account the frequency of these subsets within the CD4 compartment and their relative infection frequencies." (PMID 27415008, 2016). "However, we found that during an active immune response, such as the one induced following an infection, Areg production by in vivo-primed Treg cells is driven by combined signals from the TCR and TIGIT." (PMID 41094201, 2025). "Although we observed an elevated Ifng transcriptional level in the lungs of TIGIT antibody treated mice, how TIGIT blockade promotes the clearance of infection has not been well explained." (PMID 40526725, 2025). "However, after infection, CD103−CD8+ T cells were activated, with upregulated expression of CD69, ICOS, PD-1, and TIGIT (p < 0.05)." (PMID 41459157, 2025).
infection (continued). "Noticeably, increased tissue damage was observed only following LCMV challenge; hence, lack of TIGIT does not affect tissue integrity at steady state but only following infection." (PMID 41094201, 2025). "Infection-induced TIGIT+ repair Treg cells also did not express the tissue Treg cell markers ST2, KLRG1 or GATA3 at the transcriptional or protein level." (PMID 41094201, 2025). "Specifically, we uniquely found that senescent T cell subtypes expressing TIGIT or TIM3 were impacted by transplantation and that TIGIT+ EM CD4 T cells, in conjunction with induction type, could predict development of infection." (PMID 40475763, 2025). "As the expression of immune checkpoint molecules on the DC may contribute to tolerogenic DCs inhibitory properties, we analyzed PD-1, TIGIT, LAG3, and CD244 expressions in cDCs and pDCs in the livers of mice at 24 weeks after infection." (PMID 38787028, 2024). "PD-1 and TIGIT expression on CD8+ T cells at 2-4 weeks post-infection did not affect humoral immunity." (PMID 39355257, 2024). "Furthermore, the expression of inhibitory receptors such as CTLA‐4, PD‐1, TIGIT, TIM‐3 and NKG2A on CD8+ T cells was found to increase during early infection." (PMID 39228012, 2024). "In addition, the expression of inhibitory receptors on CD8+ T cells, including PD-1, TIM-3, TIGIT, CTLA-4, and NKG2A were increased in the early phase after infection." (PMID 37533853, 2023). "With that in mind, the lack of effect of TIGIT blockade during infection with it suggests that it does play a role in TIGIT-mediated immune evasion." (PMID 35513379, 2022). "Additionally, at different stages of infection, CD96−CD226+ cells among NK cells, TIGIT+NK and TIGIT−NK cells significantly diminished, while CD96+CD226− cells expanded (all P < 0.05)." (PMID 33717085, 2021). "Moreover, the frequency of CD38 and HLA-DR-coexpressing TIGIT+NK and TIGIT−NK cells, correlated positively with HIV-1 viral load, but had fewer CD4 T-cell counts in the first, third and twelfth month of infection." (PMID 33717085, 2021). "Additionally, there were fewer functional TNF-α+CD107a+IFN-γ+NK cells among TIGIT+NK cells and TIGIT−NK cells in HIV-1-infected individuals in the first, third and twelfth month of infection than healthy donors." (PMID 33717085, 2021). "CD96+CD226+ cells among NK cells especially TIGIT+NK cells did not significantly expand at different stages of infection, while these cells among TIGIT−NK cells increased in the first month of infection and in chronic infection over 2 years (all P < 0.05)." (PMID 33717085, 2021). "The surface protein TIGIT (T cell immunoglobulin and immunoreceptor tyrosine-based inhibitory motif (ITIM) domain) has been characterized as an important regulator of cell-mediated immune responses in various infections." (PMID 33629951, 2021). "Interestingly, especially in the first month of infection, the decrease in CD4 T-cell counts was related to the proliferation of NK cells, including both TIGIT+ and TIGIT− subsets." (PMID 33717085, 2021). "Yet, TIGIT modulation did not affect overall numbers of IL-10-Thy1.1+ T cells in the spleen in any of the infection models." (PMID 32152316, 2020). "Taken together, these findings further support the notion that the differences in tissue damage during PR8 infection were not a result of differential virus replication in the tissue, but rather the consequence of TIGIT-dependent immune modulation." (PMID 32152316, 2020). "Here, we could detect an elevated PD-1/TIGIT co-expression on HCV-specific CD4+ T cells of acutely and chronically infected patients compared to patients with spontaneously resolved infections." (PMID 31337800, 2019). "Similarly to CD4 CM t cells, with the addition of ATG induction as a co-variate we found that the combination of lower level of EM TIGIT+ in the absence of ATG induction was the strongest predictor of freedom from infection (p ≤ 0.05)." (PMID 40475763, 2025).
infection (continued). "We did not examine TIGIT expression following infection with ALS6∆/∆, ALS7∆/∆, and ALS9∆/∆ mutants." (PMID 39109867, 2024). "Importantly, TIGIT blockade did not reduce fungal burden during infection when the Als mutant strains were used." (PMID 35513379, 2022). "Another surprising finding rising from the data presented here is the paradoxical effect of TIGIT blockade during infection with the als6Δ/Δ C. albicans strain but not with other Als mutant strains, in which we observed increased fungal burden following TIGIT blocking." (PMID 35513379, 2022). "In contrast, TIGIT or LAG-3 cell surface levels did not increase upon NL4-3 infection." (PMID 34358561, 2021). "Similarly, except for the 6th week after infection, CD4+TIGIT+ T cells also had the same changes, indicating that T. gondii infection stimulated the host TIGIT+ TEM cells to proliferate, migrate to the inflammatory surrounding tissue, and produce cytokines to control T. gondii infection." (PMID 34421855, 2021). "Interestingly, TIGIT engagement reduced infection-induced pathology independent of viral clearance, leading us to hypothesize that TIGIT may exert a tissue-protective function that is independent of its immune-suppressive properties." (PMID 41094201, 2025). "As the Areg-secreting TIGIT+ Treg cells are not LCMV-specific, this is likely driven by self-antigens released from damaged tissues following infection." (PMID 41094201, 2025). "Regardless of the timepoint or infection status, HLA-DR, CD39, TIGIT, and PD-1 were more highly expressed on MAIT cells in the BAL compared to the PBMC, consistent with some of the findings with conventional T cells in HIV+ individuals." (PMID 32433713, 2020). "Furthermore, we show that TIGIT expression in Treg cells, but not in CD8+ T cells, is essential for limiting tissue damage following infection." (PMID 41094201, 2025).